TRIM37 (tripartite motif containing 37)
Diseases named in the same sentence as TRIM37 in open-access papers (continued):
Sharing a sentence is not in itself a finding about the gene and the disease.
gallbladder cancer (2 papers, 2023 to 2024). "Controversial studies have reported that TRIM37 knockdown reduced the proliferation, clonogenicity, migration, and invasion ability of tumor cells and suppressed tumor growth in vivo, indicating the promoting effect of TRIM37 in PCa, OC, and gallbladder cancer progression." (PMID 39349439, 2024).
liver cancer (2 papers, 2022 to 2025). An epithelial or non-epithelial malignant neoplasm that arises from the liver. "Our results indicated that the increased expression of TRIM28, TRIM37, TRIM45, and TRIM59 in liver cancer tissues likely plays a pivot role in HCC." (PMID 35142083, 2022).
non-small cell lung carcinoma (2 papers, 2018 to 2022). A group of at least three distinct histological types of lung cancer, including non-small cell squamous cell carcinoma, adenocarcinoma, and large cell carcinoma. "The association of TRIM37 with NF-κB signaling pathway has been demonstrated in non-small-cell lung cancer." (PMID 30586926, 2018). "A link between the NF-κB pathway and TRIM37 was also described in the context of non-small-cell lung cancer, where NF-κB is constitutively activated." (PMID 30586926, 2018). "TRIM37 has been demonstrated to participate in the polyubiquitination of TRAF2 at the position of lysine 63, eventually leading to the activation of the NF-κB pathway in non-small cell lung cancer." (PMID 35163097, 2022).
triple-negative breast carcinoma (2 papers, 2023 to 2025). An invasive breast carcinoma which is negative for expression of estrogen receptor (ER), progesterone receptor (PR), and human epidermal growth factor receptor 2 (HER2). "TRIM37 has been shown to promote chemoresistance and metastasis in triple-negative breast cancer." (PMID 39086683, 2023).
viral infection (2 papers, 2022 to 2023). "Taken together, our data show that the FINmajor variant of Trim37 leads to poor protective antibody responses upon viral infection or vaccination, which may account for the severe respiratory tract infections often observed with Mulibrey nanism patients." (PMID 37528081, 2023). "Interestingly, a recent study showed that TRIM37 enhances the ubiquitination of TRAF6, and the knockout of TRIM37 decreases the proinflammatory cytokine production by macrophages during viral infection." (PMID 35163097, 2022). "Similarly, conditional knockout of Trim37 in T cells led to significantly decreased TFH differentiation, GC formation, and plasma cell differentiation in the lung draining lymph nodes 12 days after PR8 virus infection." (PMID 37528081, 2023).
acute lymphoblastic leukemia (1 paper, 2022). Leukemia with an acute onset, characterized by the presence of lymphoblasts in the bone marrow and the peripheral blood. "However, the role of TRIM37 in T-cell acute lymphoblastic leukemia (T-ALL) remains unclear." (PMID 36923153, 2022).
antibody deficiency (1 paper, 2023). "By constructing multiple Trim37 mutant mice (FINmajor, Trim37ko, Trim37cko, Trim37C18R/C18R, Trim37G322V/G322V), we found that respiratory tract infections and antibody deficiency in Mulibrey nanism patients could be ascribed to TRIM37-mediated regulation of protective antibody responses." (PMID 37528081, 2023).
asthma (1 paper, 2018). "TRIM37 was also shown to be involved in airway smooth muscle cell (ASMC) proliferation and migration, and thus in the progression of asthma." (PMID 30586926, 2018). "TRIM37 expression was significantly decreased in proliferating airway smooth muscle cells, while overexpression of TRIM37 suppressed PDGF-BB-induced proliferation and migration by suppressing the Wnt/β-catenin signaling pathway, with repercussions in asthma." (PMID 30586926, 2018).
cervical squamous cell carcinoma (1 paper, 2025). A squamous cell carcinoma arising from the cervical epithelium. "The TCGA database was used to show that the expression of the TRIM37 gene in cervical squamous cell carcinoma (CESC) was notably higher in primary tumor samples (n = 305) compared to normal samples (n = 3)." (PMID 40158112, 2025).
cholecystolithiasis (1 paper, 2023). Single or multiple, ovoid or irregular, solid particles that are formed from bile, cholesterol, and calcium in the gallbladder cavity. "A higher level of TRIM37 expression was detected in GBC tissues than in cholecystolithiasis tissues." (PMID 37379772, 2023).
colon cancers (1 paper, 2022). "TRIM37 has been implicated in many types of cancers, and the knockdown of TRIM37 has been shown to reduce the tumor burden in a wide range of cancers, including lung, liver, and colon cancers." (PMID 35163097, 2022).
constrictive pericarditis (1 paper, 2023). A heart disorder in which the pericardial sac becomes thickened and fibrotic, tightening the myocardium and impeding the normal myocardial function. "The Mulibrey (Muscle–liver–brain–eye) nanism caused by loss-of-function variants in TRIM37 gene is an autosomal recessive disorder characterized by severe growth failure and constrictive pericarditis." (PMID 37528081, 2023).
fatty liver disease (1 paper, 2016). A reversible condition wherein large vacuoles of triglyceride fat accumulate in liver cells via the process of steatosis. "The liver findings in mice are in line with the observation that deficient TRIM37 function leads to fatty liver disease." (PMID 27044324, 2016).
fibrous dysplasia of (1 paper, 2016). "Neither could we in Trim37−/− mice identify structural abnormalities such as fibrous dysplasia of the long bones, encountered in approximately one fourth of the human patients." (PMID 27044324, 2016).
influenza (1 paper, 2023). An acute viral infection of the respiratory tract, occurring in isolated cases, in epidemics, or in pandemics; it is caused by serologically different strains of viruses (influenzaviruses) designated A, B, and C, has a 3-day incubation period, and usually lasts for 3 to 10 days. "We found that Trim37 exerts a remarkable impact on the TFH cell response and the production of neutralizing antibodies against influenza infection in the Trim37 mutant mice." (PMID 37528081, 2023). "Trim37 prolongs the stability of Bcl6 dependent on its E3 Ub ligase activity, while Trim37 mutant mice carrying the enzymatically inactive Trim37C18R display a diminished ability to differentiate into TFH cells and an insufficient production of anti-influenza high-affinity antibodies." (PMID 37528081, 2023).
leukemia (1 paper, 2025). A malignant (clonal) hematologic disorder, involving hematopoietic stem cells and characterized by the presence of primitive or atypical myeloid or lymphoid cells in the bone marrow and the blood. "Notably, TRIM37 polymorphic variants have previously been associated with leukemia (rs11656413,), schizophrenia ((rs4968363, rs2877926,), and inflammatory bowel." (PMID 39614126, 2025).
liver fibrosis (1 paper, 2024). "TRIM37 facilitates liver fibrosis by interacting with SMAD7 and promoting ubiquitin degradation." (PMID 39199424, 2024). "Meanwhile, the HBV-mediated transcriptional activation of NF-κB promotes TRIM37 expression and, in turn, its expression is induced by HBx protein-produced ROS, which are located upstream of TRIM37 and also promotes the transcriptional activity of NF-κB and aggravates liver fibrosis." (PMID 39199424, 2024).
metabolic syndrome (1 paper, 2024). A cluster of metabolic risk factors for CARDIOVASCULAR DISEASES and TYPE 2 DIABETES MELLITUS. "In the scenario of metabolic liver disease, it has been reported that loss-of-function mutations in the peroxisomal/nuclear protein TRIM37 cause a monogenic multiorgan disorder characterized by metabolic syndrome." (PMID 38206764, 2024).
metastasis (1 paper, 2021). The spread or migration of cancer cells from one part of the body (where they first appeared) to another. "Following gastrectomy, TRIM37 protein expression was significantly associated with recurrence (P =0.028), in particular lymphatic metastasis (P = 0.042)." (PMID 33391428, 2021).
non-compaction cardiomyopathy (1 paper, 2016). Left ventricular non-compaction (LVNC) is characterized by prominent left ventricular trabeculae and deep inter-trabecular recesses. "At 1.5 years Trim37−/− mice showed non-compaction cardiomyopathy, hepatomegaly, fatty liver and various tumors." (PMID 27044324, 2016).
pancreatic adenocarcinoma (1 paper, 2020). "To assess which intracellular pathways might mediate the effects of TRIM37 overexpression and silencing in PC cells, we performed Kyoto Encyclopedia of Genes and Genomes (KEGG) pathway enrichment analysis of genes in the pancreatic adenocarcinoma dataset from The Cancer Genome Atlas (TCGA)." (PMID 33194618, 2020).
renal carcinoma (1 paper, 2021). A carcinoma arising from the epithelium of the renal parenchyma or the renal pelvis. "In this study, we performed RCC microarrays chip analysis and identified one of TRIM family protein TRIM37 as an aberrant regulator in renal cancer." (PMID 34130705, 2021).
respiratory infection (1 paper, 2023). "Thus, our data demonstrate the essential role of the Trim37-Bcl6 axis in the differentiation of TFH cells that underlies the recurrent respiratory infections observed in patients with Mulibrey nanism." (PMID 37528081, 2023). "Here we establish the causality between the E3 Ub ligase TRIM37 and severe respiratory infection." (PMID 37528081, 2023). "Collectively, these findings highlight the importance of the Trim37-Bcl6 axis in controlling the development of TFH cells and the production of high-affinity antibodies, and further unveil the immunologic mechanism underlying recurrent respiratory infection in Mulibrey nanism." (PMID 37528081, 2023).
Sertoli cell tumor (1 paper, 2016). A sex cord-stromal tumor of the testis or the ovary. "Ovaries of Trim37−/− mice also showed lipid cell hyperplasia and increased incidence of both cysts and Sertoli cell tumors." (PMID 27044324, 2016). "In addition, common ovarian findings in Trim37−/− mice included cysts and Sertoli cell tumors (for more details, see paragraph ‘Increased incidence of ovarian Sertoli cell tumors in Trim37−/− females’)." (PMID 27044324, 2016).
steatosis (1 paper, 2023). Increased lipid within the cytoplasm of cells. "Over-expression of TRIM37 resulted in more severe congestion, steatosis, ballooning (above) and apoptosis (below) in the liver, indicating that an increase in TRIM37 deteriorated hepatic pathological lesions and apoptosis." (PMID 37158850, 2023).
cancer (34 papers, 2016 to 2026). A tumor composed of atypical neoplastic, often pleomorphic cells that invade other tissues. "It was recently shown that inhibition of polo-like kinase 4 (PLK4) induces synthetic lethality in cancers with chromosome 17q-encoded TRIM37 copy number gain due to cooperative regulation of centriole duplication and mitotic spindle nucleation." (PMID 42288516, 2026). "Previous studies showed that PLK4 inhibition causes synthetic lethality in cancer cells with genomic amplification or overexpression of the centrosomal ubiquitin ligase TRIM37 which is a negative regulator of PCM59–62." (PMID 38951519, 2024). "Together, our results demonstrate that TRIM37 is required for efficient transcription of AP-2γ target genes and coregulate cancer-associated genes that affect tumor progression." (PMID 35864973, 2022). "Patients with Mulibrey nanism, which is the consequence of autosomal recessive mutations in the gene encoding the TRIM37 protein, have increased the risk of both benign and malignant tumors, vascular lesions, and impaired organ development." (PMID 35163097, 2022). "TRIM37 mutations are associated with a more frequent cancer diagnosis as well as disturbed organ development, with a high number of gynecological tumors described in the literature." (PMID 30586926, 2018). "The association of TRIM37 mutations with increased cancer risk favors a prosurvival process in TRIM37-deficient tumor cells." (PMID 30586926, 2018). "Trim37−/− mice also had an increased risk of developing tumors, showing a higher frequency of both benign and malignant tumors than wild-type control animals." (PMID 27044324, 2016). "Thus, PLK4 inhibition is currently being explored in TRIM37-implicated cancers as a way to trigger selective mitotic failure for cancer treatment." (PMID 39086683, 2023). "A wide variety of cancers are associated with overexpression of TRIM37." (PMID 35310029, 2022). "TRIM37 has been reported to be associated with the tumorigenesis of cancers." (PMID 36923153, 2022). "The results found here provide novel insights by demonstrating that TRIM37 exhibits significantly elevated expression level in CC tissues and cells, confirming its role in cancer progression through rigorous experimentation." (PMID 40158112, 2025). "Here, we report that cancer-free breast tissue from Black women expresses TRIM37 at a significantly higher level relative to White women." (PMID 39614126, 2025). "As an important ubiquitinating enzyme, TRIM37 has been shown to be highly expressed in CC and to fuel cancer progression." (PMID 40158112, 2025). "The discovery of TRIM37 as a factor that confers cancer‐specific vulnerability started with the investigation of its loss‐of‐function phenotype." (PMID 40257113, 2025). "Here, we uncovered that higher TRIM37 expression in the normal, cancer-free breast tissue of BW favors transcriptional activation sufficient to induce transformation in immortalized breast epithelial cells." (PMID 39614126, 2025). "Sensitivity of cancer cells to PLK4 inhibition appears to be dependent on the levels of TRIM37 (Tripartite motif-containing protein 37) ubiquitin ligase." (PMID 41092110, 2025). "We show that TRIM37 is expressed significantly higher in the cancer-free breast tissue from BW than in WW." (PMID 39614126, 2025). "The results of previous studies suggest that tripartite motif containing 37 (TRIM37) contributes to the progression of numerous types of cancer." (PMID 37379772, 2023). "Some of these regions overlapped cancer-specific driver super enhancers (e.g., TRIM37 locus in MCF-7)." (PMID 36719906, 2023).
cancer (continued). "Studies have depicted that RNF2, BMI1, TRIM37, and other ubiquitinating genes were related to cancer progression." (PMID 37980168, 2023). "In agreement with previous findings 17, we observed TRIM37 amplified in many cancers, including BCa." (PMID 35864973, 2022). "TRIM37 dysregulation has been observed in several cancer types, implicating its possible role in tumorigenesis." (PMID 35163097, 2022). "TRIM37 is often overexpressed in a variety of cancer cells, and it has been confirmed that overexpression of TRIM37 induces cell proliferation." (PMID 34769343, 2021). "TRIM37 activity is known to modulate the expression of multiple genes, including tumor suppressors, in several types of cancers." (PMID 33194618, 2020). "TRIM37 enhances the invasion and metastasis of many cancers, including gastric cancer, glioma, and colorectal cancer, via the epithelial–mesenchymal transition." (PMID 33194618, 2020). "Existing clues suggest that the abnormal expression of some ubiquitination enzymes, like TRIM37, may interfere with iron metabolism and lipid peroxidation levels in cancer cells, implying its involvement in the regulation of ferroptosis in cervical cells." (PMID 40158112, 2025). "Next, to determine whether there is an independent contribution of TRIM37 to the neoplastic transformation in BW, we interrogated TRIM37 expression in normal, cancer-free breast tissue." (PMID 39614126, 2025). "Importantly, cancers with amplified TRIM37 became increasingly vulnerable to PLK4 inhibition, which led to mitotic failure or death." (PMID 40257113, 2025). "In addition, targeted inhibition of PLK4 has emerged as a promising therapeutic strategy in the fight against cancer, supported by recent preclinical studies investigating the synthetic‐lethal relationship between TRIM37 amplification and PLK4 inhibition." (PMID 40257113, 2025). "Moreover, existing studies have highlighted the modulatory role of TRIM37 in the ubiquitination of both onco-proteins and tumor suppressors to affect cancer development." (PMID 38842683, 2024). "The possible reason might be different cancer types and the involvement of specific substrates of TRIM37." (PMID 39349439, 2024). "Currently, growing evidence suggests that TRIM37 is an oncogene and may serve as a potential therapeutic target in human cancers." (PMID 37379772, 2023). "Upregulated expression of TRIM37 plays a critical role in cancer progression and development." (PMID 37379772, 2023). "However, when the expression of TRIM37 in cancer cells was knocked down, cell viability was significantly reduced." (PMID 35163097, 2022). "Furthermore, an in vivo study using an orthotopic syngeneic animal model further confirmed that reduced expression of TRIM37 in cancer cells suppressed tumor growth in vivo." (PMID 35163097, 2022). "TRIM37 mRNA overexpression was observed in GC cell lines and the testis compared with healthy organs and the fibroblast cell line WI-38, suggesting that this gene is a cancer-testis antigen." (PMID 33391428, 2021). "EMT is a crucially phenotypic plasticity process for migratory and invasive properties in cancer, blocking of TRIM37 significantly resulted the downregulation of mesenchymal cell markers of N-cadherin and Vimentin, as well as the upregulation of epithelial marker Claudin-1." (PMID 34130705, 2021). "In this study, we tested whether TRIM37 acts as a cancer-promoting factor by being overexpressed in GC." (PMID 33391428, 2021). "TRIM37 was observed mainly in the cytoplasm of cancer cells." (PMID 33391428, 2021). "Previous studies suggested the possibility that TRIM37 may have essential functions in various cancer types." (PMID 33194618, 2020). "Inactivation of TRIM37 results in MULIBREY nanism and predisposes to both benign and malignant tumors, with several reports revealing a positive correlation between TRIM37 overexpression and cancer." (PMID 30586926, 2018).